KCNJ11 (potassium inwardly rectifying channel subfamily J member 11)
Diseases named in the same sentence as KCNJ11 in open-access papers (continued):
Sharing a sentence is not in itself a finding about the gene and the disease.
myocardial ischemia (6 papers, 2013 to 2023). A disorder of cardiac function caused by insufficient blood flow to the muscle tissue of the heart. "Compound CL-705G is a possible lead compound to KATP channel related pathologies (such as cardiac ischemia) or to treat specific KCNJ11 missense channelopathy loss-of-function variants." (PMID 37408765, 2023). "It has been demonstrated that genetic variants of the potassium inwardly rectifying channel subfamily J member 11 (KCNJ11) gene, coding for Kir6.2, may produce alterations in K-ATP channel function, impacting myocardial ischemia susceptibility." (PMID 37240691, 2023). "In addition, the co-presence of the SNPs rs5215_G/G of KCNJ11 and rs1799983_T/T of the nitric oxide synthase 3 (NOS3) gene may play a protective role against myocardial ischemia." (PMID 37240691, 2023).
Hypertension (5 papers, 2014 to 2024). The presence of chronic increased pressure in the systemic arterial system. "The associations between variants of KCNJ11 and hypertension were demonstrated in Chinese and Korean populations, suggesting a possible role of KCNJ11 in macrovascular diseases." (PMID 25573672, 2015). "Several SNPs in KCNJ11 were initially reported to be linked to T2DM susceptibility and subsequently to vascular-related complications of T2DM such as hypertension, coronary artery disease (CAD) or diabetic retinopathy." (PMID 36314849, 2022). "The risk of hypertension is related to the NRBP1, REG4, CCNE2, and KCNJ11 genes." (PMID 38915894, 2024). "Minoxidil had the most negative correlation coefficient (−0.3101) and is a hypertension medication that targets KCNJ8, KCNJ11, and ABCC9." (PMID 39713369, 2024).
diabetic ketoacidosis (4 papers, 2017 to 2024). The metabolic condition resulted from uncontrolled diabetes mellitus, in which the shift of acid-base status of the body toward the acid side because of loss of base or retention of acids other than carbonic acid is accompanied by the accumulation of ketone bodies in body tissues and fluids. "We present a case of NDM in a proband initially presenting with focal seizures and diabetic ketoacidosis due to a pathologic mutation in the beta cell potassium ATP channel gene KCNJ11 c.679G > A (p.E227K)." (PMID 37664823, 2023). "Case 1 (male, 18 years, compound heterozygous ABCC8 mutation) and case 2 (female, 29 years, heterozygous KCNJ11 mutation) presented with severe diabetic ketoacidosis at 6 and 16 weeks of age." (PMID 28173619, 2017). "The patient in Case 3 (a 14-year-old boy) had a variation in the KCNJ11 gene (MODY 13) and presented with diabetic ketoacidosis; after initially being treated as having T1DM, he developed progressive weight gain, acanthosis nigricans, and decreased requirement of insulin." (PMID 39420905, 2024).
diabetic retinopathy (4 papers, 2015 to 2022). "This work represents an advance in biomedical science because it represents new data about association of Diabetic Retinopathy with c.67A>G as a key SNP of KCNJ11 among T2DM patients." (PMID 35996512, 2022). "Genome-wide association studies have found polymorphism in KCNJ11 (rs5219) to be associated with diabetic retinopathy which may be related to the visual disturbances association identified in the current study." (PMID 27535653, 2016).
hepatocellular carcinoma (4 papers, 2017 to 2024). A malignant tumor that arises from hepatocytes. "Former studies have verified that KCNJ11, the encoding gene of kir6.2 protein, is regulated by NF-κB signaling in hepatocellular carcinoma and p38 MAPK/PKC signal pathways in AD." (PMID 33584303, 2020).
prediabetes (4 papers, 2011 to 2023). "Multinomial logistic regression analysis showing the association of the KCNJ11 E23K variant with progression to prediabetes and progression to T2DM at the end of the 12-year study." (PMID 22163043, 2011). "In the current study, the KCNJ11 E23K variant was shown to be associated with glycaemic progression, in the development of prediabetes from NGT." (PMID 22163043, 2011). "Multiple multinomial logistic regression showing the association of the KCNJ11 E23K variant with progression to prediabetes and progression to T2DM, adjusted for confounding factors." (PMID 22163043, 2011). "The KCNJ11 E23K variant was associated with the progression to prediabetes after a median interval of 12 years on multinomial logistic regression analysis, even after adjustment for traditional risk factors (OR 1.29, Page, sex, BMI and fasting plasma glucose [FPG] adjusted = 0.02)." (PMID 22163043, 2011). "Cox regression analysis showing the association the KCNJ11 E23K variant with incident prediabetes." (PMID 22163043, 2011).
) channelopathies (3 papers, 2020 to 2026). "Can CL-705G restore the activity of loss-of-function KCNJ11 channelopathies?" (PMID 37408765, 2023). "The most profound application of precision medicine in NDM is the treatment of KCNJ11 and ABCC8 channelopathies." (PMID 41614934, 2026).
glioma (3 papers, 2024 to 2026). A benign or malignant brain and spinal cord tumor that arises from glial cells (astrocytes, oligodendrocytes, ependymal cells). "The AQP4 aggregation state similarly and significantly caused an upregulation of the KCNJ11, ABCC8, and ABCC9 genes in U87 glioma cells." (PMID 39200356, 2024). "Conducting an extensive search using PubMed on glioma/brain-cancer-related articles of ABCC8, ABCC9, KCNJ11, KCNJ8, AQP4, and KCNMA1 genes has yielded interesting results." (PMID 39200356, 2024). "In the present work, we showed that the AQP4 aggregation into the pathogenic AQP4-tetramer and AQP4-OAPs differently affected the expression profile of KCNMA1, KCNJ11, ABCC8, and ABCC9 genes but not of the KCNJ8 gene in the U87 glioma cell, evaluated by the RTPCR gene expression." (PMID 39200356, 2024).
Stroke (3 papers, 2023 to 2026). Sudden impairment of blood flow to a part of the brain due to occlusion or rupture of an artery to the brain. "And then colocalization analysis was performed for sulfonylureas with any stroke, and any ischemic stroke within the drug target encoding genes (± 2500 base pairs of KCNJ11 and ABCC8 )." (PMID 37777789, 2023). "Using 0.7 as a posterior probability threshold, a high probability of shared casual variants for blood glucose and stroke within the encoding genes for sulfonylureas (KCNJ11 and ABCC8) was suggested." (PMID 37777789, 2023). "Colocalization analysis for sulfonylureas with any stroke and any ischemic stroke within the drug target encoding genes (± 100 kb of KCNJ11 and ABCC8 ) were performed." (PMID 37777789, 2023). "Colocalization supported shared casual variants for blood glucose with any stroke and any ischemic stroke within the encoding genes for sulfonylureas targets (KCNJ11 and ABCC8) (posterior probability>0.7)." (PMID 37777789, 2023). "This study demonstrated that sulfonylureas were linked to adecreased risk of both stroke and ischemic stroke, which is consistent with ourfindings, whereby elevated KCNJ11 (the target gene of sulfonylureas)expression is associated with an increased risk of AIS." (PMID 41209129, 2025).
Anxiety (2 papers, 2025 to 2026). Intense feelings of nervousness, tension, or panic often arise in response to interpersonal stresses. "Our conclusions are further supported by clinical studies where individuals with KCNJ11 mutations report higher incidences of problems with sleep, anxiety, and attention." (PMID 39964713, 2025).
anxiety disorder (2 papers, 2016 to 2026). A category of psychiatric disorders which are characterized by anxious feelings or fear often accompanied by physical symptoms associated with anxiety. "Neurodevelopmental disorders (autism and ADHD) and/or anxiety disorders were present in all six children with sulfonylurea‐treated neonatal diabetes due to V59M or R201C KCNJ11 mutations." (PMID 27086753, 2016). "Although families affected by KCNJ11-NDM may have a high risk of anxiety disorders, it is encouraging that affected and unaffected children exhibit robust self-resiliency that will help support functioning through the challenges of life." (PMID 41591478, 2026).
astrocytoma (2 papers, 2025 to 2026). "Analysis of the SHAP values for the remaining genes revealed that increased expression of ZDHHC18, HDAC1, and TUBB6 enhances the probability of predicting astrocytoma, while elevated expression of TERT, TRIM67, NOG, KCNIP2, and KCNJ11 increases the probability of predicting oligodendroglioma." (PMID 40867242, 2025).
Cerebral ischemia (2 papers, 2013 to 2016). Restriction of arterial blood supply to the brain associated with insufficient oxygenation to support the metabolic requirements of the tissue. "Utilizing the BV2 microglial cell line, they reported induction of Abcc8/Sur1 and Kcnj11/Kir6.2 following exposure to LPS + IFNγ for 48 h, as well as enhanced immunolabeling of microglia in vivo for subunits of Sur1-Kir6.2 (KATP) in cerebral ischemia." (PMID 27246103, 2016).
coronary artery disease (2 papers, 2021 to 2022). "Endothelial nitric oxide synthase (eNOS) and potassium voltage-gated channel subfamily J member 11 (KCNJ11) could be the candidate genes for coronary artery disease (CAD)." (PMID 35222579, 2021).
epithelial ovarian cancer (2 papers, 2020 to 2023). "This investigation revealed that both Kir6.2 (KCNJ11) and SUR2 (ABCC9) proteins can be expressed in ovarian cancer." (PMID 32457608, 2020).
ischemic stroke (2 papers, 2023 to 2025). A stroke disorder caused by obstruction of blood flow to the brain, due to thrombotic (local blood clot formation) or embolic (due to a blood clot or other material traveling from another site) event. "Specifically, increased expression of KCNJ11 (the targetgene of sulfonylureas) and SLC5A2 (the target gene of SGLT2 inhibitors)was associated with a heightened risk of ischemic stroke." (PMID 41209129, 2025).
maturity-onset diabetes of the young type 13 (2 papers, 2025). Any maturity-onset diabetes of the young in which the cause of the disease is a mutation in the KCNJ11 gene. "This patient's specific variant, c.679G>A (p.Glu227Lys) in KCNJ11, has been seen in MODY type 13 and is inherited in an autosomal dominant manner." (PMID 40309172, 2025).
pancreatic cancer (2 papers, 2023 to 2024). "In addition, the mediation effect of BMI on the causal connection between ABCC8/KCNJ11 and pancreatic cancer risk was detected." (PMID 38504335, 2024). "ABCC8/KCNJ11 were observed sharing gene regions with pancreatic cancer risk (PP4 = 0.836)." (PMID 38504335, 2024). "Associations of ABCC8/KCNJ11, DPP4, GLP1R, GPD2, PPARG, PRKAB1, and SLC5A2 with anal carcinoma, cardia cancer, gastric cancer, HCC, ICC, pancreatic cancer, and rectum cancer were revealed in two-sample MR analyses." (PMID 38504335, 2024). "This was in harmony with our study where ABCC8/KCNJ11 was correlated with a higher risk of ICC and pancreatic cancer, as well as a lower risk of anal carcinoma and HCC." (PMID 38504335, 2024). "The mediation effect of body mass index (OR: 0.938; 95% CI: 0.884–0.995; proportion of mediation effect: 3.001%; P-value = 0.033) on ABCC8/KCNJ11 and pancreatic cancer was uncovered." (PMID 38504335, 2024). "In SMR analyses, ABCC8/KCNJ11, DPP4, PPARG, ETFDH, and PRKAB1 were associated with anal carcinoma, cardia cancer, and pancreatic cancer." (PMID 38504335, 2024). "Furthermore, BMI played a mediation role in the correlation between ABCC8/KCNJ11 and pancreatic cancer via the mediation MR analyses." (PMID 38504335, 2024). "Furthermore, ABCC8/KCNJ11, DPP4, GLP1R, PRKAB1, and GPD2 shared causal variants within anal cancer, HCC, ICC, pancreatic cancer, and rectum cancer according to the colocalization analyses." (PMID 38504335, 2024). "The promoting effect of ABCC8/KCNJ11 on pancreatic cancer was also observed in SMR analysis." (PMID 38504335, 2024). "Simultaneously, the colocalization analyses revealed that ABCC8/KCNJ11 shared identical genetic regions with anal carcinoma, HCC, ICC, and pancreatic cancer." (PMID 38504335, 2024).
ventricular tachycardia (2 papers, 2015 to 2025). A disorder characterized by an electrocardiographic finding of three or more consecutive complexes of ventricular origin with a rate greater than a certain threshold (100 or 120 beats per minute are commonly used). "Second, due to the limitations of the original GWAS data, we were unable to further explore the association between KCNJ11/ABCC8 and subtypes of PT (e.g., ventricular tachycardia, supraventricular tachycardia)." (PMID 41357784, 2025).
anal carcinoma (1 paper, 2024). "Strong evidence suggested colocalization between DPP4, GLP1R, ABCC8/KCNJ11, and anal carcinoma." (PMID 38504335, 2024).
atrial fibrillation (1 paper, 2025). A disorder characterized by an electrocardiographic finding of a supraventricular arrhythmia characterized by the replacement of consistent P waves by rapid oscillations or fibrillatory waves that vary in size, shape and timing and are accompanied by an irregular ventricular response. "Mendelian randomization analyses suggest that genetic proxies for antidiabetic drug targets—KCNJ11/ABCC8, SLC5A2, and RXRB—reduce the risk of paroxysmal tachycardia (PT), right bundle branch block (RBBB), and atrial fibrillation (AF), respectively." (PMID 41357784, 2025).
attention deficit-hyperactivity disorder (1 paper, 2025). A disorder characterized by a marked pattern of inattention and/or hyperactivity-impulsivity that is inconsistent with developmental level and clearly interferes with functioning in at least two settings (e.g. at home and at school). "Patients with KCNJ11 variants may present with attention deficit hyperactivity disorder (ADHD), autism spectrum disorder (ASD), developmental coordination disorder (DCD), and learning difficulties due to diminished intelligence quotient (IQ) and dyslexia." (PMID 41169283, 2025).
brain tumor (1 paper, 2016). "Importantly, activation of Ca2+-activated BKCa K+ channels (encoded by the KCNMA1 gene) and ATP-sensitive Kir6.2 (encoded by the KCNJ11 gene) K+ channels in brain endothelial and brain tumor cells has been demonstrated in animal models to increase the permeability of the BBTB." (PMID 27618016, 2016).
cardia cancer (1 paper, 2024). A malignant neoplasm involving the cardia of stomach. "Risk of cardia cancer was connected with KCNJ11 (OR = 0.229; 95% CI: 0.059–0.884; P-value = 0.032) and PPARG (OR = 2.813; 95% CI: 1.239–6.388; P-value = 0.013)." (PMID 38504335, 2024).
dyslipidemia (1 paper, 2021). "Genotyping UCP2 and probably KCNJ11 may help to select the optimal antidiabetic therapy and improve disease prognosis, whereas the MTHFR gene may determine the need to monitor group B vitamin status and the risk of dyslipidemia." (PMID 34289004, 2021).
early-onset epilepsy (1 paper, 2023). "Syndromes characterized by neonatal-onset diabetes and early-onset epilepsy are described (mutations in GCK, INS, KCNJ11, and ABCC8)." (PMID 37048663, 2023).
insulin resistance diabetes (1 paper, 2024). "Potassium inwardly rectifying channel subfamily J member 11 (KCNJ11) is a target most closely related to T2DM in our study and also an achievement based on the precise treatment of monogenic insulin deficiency and insulin resistance diabetes in the new century." (PMID 38915894, 2024).
Klinefelter syndrome (1 paper, 2018). A sex chromosome disorder caused by the presence of an extra X chromosome in the male karyotype. "We report transient neonatal diabetes due to a pathogenic heterozygous variant in KCNJ11 in a male infant with Klinefelter syndrome." (PMID 28766502, 2018). "This case is the first due to a mutation in the KCNJ11 as the previously reported case of transient neonatal diabetes and Klinefelter syndrome had uniparental heterodisomy of chromosome 6." (PMID 28766502, 2018).
mucinous ovarian cancer (1 paper, 2026). An invasive malignant neoplasm that arises from the ovary and is characterized by the presence of malignant epithelial cells that contain intracytoplasmic mucin and may resemble the epithelial cells of the endocervix or gastrointestinal tract. "We then performed cis drug-target MR for PPARG, DPP4, ABCC8/KCNJ11, and SLC5A2, integrated triangulation, colocalization, and mediation analyses, and experimentally interrogated the prioritized PPARG/ABCC8-KCNJ11-lactate-invasive mucinous ovarian cancer (IMOC) triangle." (PMID 42278567, 2026).
paroxysmal tachycardia (1 paper, 2025). A form of tachycardia which begins and ends in an acute (or paroxysmal) manner. "Sulfonylurea targets KCNJ11/ABCC8 were associated with a decreased incidence of paroxysmal tachycardia (OR: 0.69, 95% CI: 0.56, 0.86, PFDR = 0.022)." (PMID 41357784, 2025). "SMR analysis indicated that lowered expression of KCNJ11 was related to a decreased paroxysmal tachycardia risk (OR: 1.05, 95% CI: 1.01, 1.08, PSMR = 0.010), further confirming the role of KCNJ11 in paroxysmal tachycardia." (PMID 41357784, 2025).
primary hypertension (1 paper, 2025). "The KCNJ11 rs5219 may be associated with susceptibility to primary hypertension in the Kazakh population in Xinjiang." (PMID 39854379, 2025).
renal carcinoma (1 paper, 2025). A carcinoma arising from the epithelium of the renal parenchyma or the renal pelvis. "The high KCNJ11 gene expression is associated with favorable prognostic and life expectancy in renal cancer (data available from The Human Protein Atlas, version 23.0)." (PMID 40149317, 2025).
skin cancer (1 paper, 2024). "Insufficient evidence was found for the associations between genetically proxied GLP1R, KCNJ11, ABCC8, and PPARG perturbations and skin cancer risk." (PMID 39640975, 2024).
uterine corpus endometrial carcinoma (1 paper, 2023). A endometrial carcinoma (disease) that involves the body of uterus. "The KCNJ11 gene was significantly associated with negative prognosis in Asian males, black men, and black females in liver hepatocellular carcinoma, kidney renal papillary cell carcinoma, and uterine corpus endometrial carcinoma, respectively." (PMID 37180726, 2023). "The KCNJ11 gene was significantly associated with a negative prognosis in Asian males, black men, and black females in liver hepatocellular carcinoma, kidney renal papillary cell carcinoma, and uterine corpus endometrial carcinoma." (PMID 37180726, 2023).
tumor (7 papers, 2005 to 2025). "KCNJ11 expression was related to the degree of tumor malignancy and was an independent factor that affected the OS, and survival times of patients with high expression of KCNJ11 were longer than those of patients with low expression." (PMID 40867242, 2025). "By combining these gene sets, we identified the leading genes that were associated with the tumor laterality: CACNA1C, CACNA2D2, CACNB2, KCNJ11, SCN3A, and SCN3B, signature that we called: 6-ICH signature." (PMID 37446299, 2023). "Significant anti-tumor effects were observed based on these groupings, and the high expression group of CCKBR and KCNJ11 showed better anti-tumor effects." (PMID 34675134, 2021).
cancer (6 papers, 2012 to 2024). A tumor composed of atypical neoplastic, often pleomorphic cells that invade other tissues. "This study revealed that the KCNJ8, KCNJ11, ABCC8, ABCC9 genes are downregulated in cancer of the female reproductive tract when compared with the correspondent normal tissues." (PMID 32457608, 2020). "The minoxidil-induced overactivation of Kir6.1/2-Sur2A/B subunits in rats provoked a cancer reaction similar to what was observed in some cases of C.S. Omics data reporting the upregulation of the ABCC9, KCNJ11, and KCNJ8 genes in cancers support these conclusions." (PMID 37180726, 2023). "Also, pharmacovigilance data were analyzed to assess the correlation of ABBC8, ABCC9, KCNJ11, and KCNJ8 genes with cancer reactions induced by drugs targeting the different KATP channel subunits." (PMID 37180726, 2023). "KCNJ11, KCNJ8, and ABCC9 genes are upregulated in cancers but ABCC8 is downregulated." (PMID 37180726, 2023).